ZNF592 (zinc finger protein 592)
Description:
May be involved in transcriptional regulation.
Synonyms: KIAA0211; CAMOS; SCAR5
Tractability: PROTAC: UniProt records ubiquitination sites on it; ubiquitination databases record sites on it; its protein half-life has been measured.
Gene: Protein-coding gene on chromosome 15 (84,748,362 to 84,806,445, forward strand). Ensembl gene ENSG00000166716.
Subcellular location: Nucleus
Subcellular location (Human Protein Atlas): Nucleoplasm
Pathways (Reactome):
Chromatin organization: Interaction of NuRD complexes with transcription factors
Gene Ontology:
Molecular function: protein binding; DNA-binding transcription factor activity; insulin receptor substrate binding; PH domain binding
Biological process: regulation of DNA-templated transcription
Cellular component: nucleoplasm; nucleus
Genetic constraint (gnomAD): Loss-of-function variants: 11 observed, 85.98 expected, observed/expected ratio (o/e) 0.13, 90% interval 0.08 to 0.21. The upper end of that interval is the gene's LOEUF score, 0.21, which puts it in group 1 of 6, group 1 being the genes least tolerant of losing a copy. Missense variants: 1,420 observed, 1,709.2 expected, observed/expected ratio (o/e) 0.83, 90% interval 0.79 to 0.87. Synonymous variants: 646 observed, 669.37 expected, observed/expected ratio (o/e) 0.97, 90% interval 0.9 to 1.03.
Homologues: Orthologues: chimpanzee ZNF592 (99% identical), dog ZNF592 (91% identical), pig ZNF592 (91% identical), rabbit ZNF592 (90% identical), mouse Zfp592 (88% identical), rat Zfp592 (87% identical), guinea pig ZNF592 (86% identical), tropical clawed frog znf592 (53% identical), zebrafish znf592 (42% identical). Paralogues in human: ZNF687 (31% identical), PRDM2 (14% identical), ZNF407 (10% identical), ZBTB17 (10% identical), ZKSCAN7 (10% identical), ZNF852 (10% identical), ZNF287 (10% identical), ZNF34 (10% identical), ZNF527 (9% identical), ZNF214 (9% identical), ZNF416 (9% identical), ZNF333 (9% identical), and 38 more.
Diseases named in the same sentence as ZNF592 in open-access papers:
ZNF592 is named in the same sentence as 15 diseases in open-access papers, as found by Europe PMC text mining. Sharing a sentence is not in itself a finding about the gene and the disease. The quoted sentences say what the papers report.
breast carcinoma (1 paper, 2021). "The influence of ZMYND8 on cancer cell invasion and metastasis is related to the interaction between ZMYND8, TROJAN, and ZNF592 in breast cancer." (PMID 33670804, 2021). "In MDA-MB-231 LM2 breast cancer cells, TROJAN binds to ZMYND8, and increases its degradation through the ubiquitin-proteasome pathway, by repelling ZNF592." (PMID 33670804, 2021).
cerebellar ataxia (1 paper, 2024). A neurological syndrome characterized by clumsy and uncoordinated movement of the limbs, trunk, and cranial muscles. "ZNF592 was initially thought to be responsible for autosomal recessive spinocerebellar ataxia 5 from a consanguineous family with neurodevelopmental delay including cerebellar ataxia and intellectual disability due to a homozygous G1046R substitution." (PMID 39152475, 2024).
Galloway-Mowat syndrome (1 paper, 2024). Galloway syndrome is characterized by the association of nephrotic syndrome and central nervous system anomalies. "However, further analysis of this family identified WDR73 to be the most likely causative gene, consistent with Galloway-Mowat syndrome, although ZNF592 may have contributed to the phenotype." (PMID 39152475, 2024).
tumor (1 paper, 2021). "For example, the interaction between ZMYND8 and PKCβ or TROJAN may induce pro-oncogenic effects, while interaction between ZMYND8 and KDM5C, KDM5D, or ZNF592 may cause tumor-suppressive effects." (PMID 33670804, 2021).
ZNF592 also shares sentences with these, for which no sentence is quoted: attention deficit-hyperactivity disorder (1 paper); autism spectrum disorder (1); bipolar disorder (1); brain disorder (1); CAMOS syndrome (1); generalized anxiety disorder (1); Intellectual disability (1); obsessive-compulsive disorder (1); optic atrophy (1); schizophrenia (1); unipolar depression (1).